NPTX2 (neuronal pentraxin 2)
Description:
Likely to play role in the modification of cellular properties that underlie long-term plasticity. Binds to agar matrix in a calcium-dependent manner (By similarity).
Synonyms: NP2; NP-II; NARP
Tractability: Antibody: UniProt places it where antibodies can reach, with medium confidence; UniProt predicts a signal peptide or a membrane-spanning region; its Gene Ontology location is reachable by antibodies, with medium confidence.
Gene: Protein-coding gene on chromosome 7 (98,617,285 to 98,629,869, forward strand). Ensembl gene ENSG00000106236.
Subcellular location: Secreted
Subcellular location (Human Protein Atlas): Actin filaments; Golgi apparatus; Centrosome; Predicted to be secreted
Gene Ontology:
Molecular function: protein binding
Biological process: chemical synaptic transmission
Cellular component: glutamatergic synapse; extracellular region; presynapse; synapse
Genetic constraint (gnomAD): Loss-of-function variants: 22 observed, 28.77 expected, observed/expected ratio (o/e) 0.76, 90% interval 0.55 to 1.09. The upper end of that interval is the gene's LOEUF score, 1.09, which puts it in group 4 of 6, group 1 being the genes least tolerant of losing a copy. Missense variants: 434 observed, 420.38 expected, observed/expected ratio (o/e) 1.03, 90% interval 0.95 to 1.12. Synonymous variants: 231 observed, 194.11 expected, observed/expected ratio (o/e) 1.19, 90% interval 1.07 to 1.33.
Homologues: Orthologues: chimpanzee NPTX2 (100% identical), macaque NPTX2 (99% identical), mouse Nptx2 (96% identical), dog NPTX2 (96% identical), rat Nptx2 (96% identical), pig NPTX2 (94% identical), guinea pig NPTX2 (85% identical), tropical clawed frog nptx2 (73% identical), zebrafish nptx2a (66% identical), rabbit NPTX2 (64% identical), zebrafish nptx2b (62% identical). Paralogues in human: NPTX1 (54% identical), PTX4 (27% identical), PTX3 (19% identical), CRP (15% identical), APCS (14% identical).
Diseases named in the same sentence as NPTX2 in open-access papers:
NPTX2 is named in the same sentence as 110 diseases in open-access papers, as found by Europe PMC text mining. Sharing a sentence is not in itself a finding about the gene and the disease. The quoted sentences say what the papers report.
Alzheimer disease (29 papers, 2017 to 2025). A progressive, neurodegenerative disease characterized by loss of function and death of nerve cells in several areas of the brain leading to loss of cognitive function such as memory and language. "Decreased NPTX2 level has been reported to be associated with diverse neurological diseases, including Alzheimer’s disease, anxiety, vascular dementia, Parkinson’s disease and ischemia." (PMID 35310542, 2021). "In line with our results, higher NPTX2, a proinflammatory protein involved in synaptic plasticity, was previously associated with higher CSF Aβ1–42 in the Alzheimer’s Disease Neuroimaging Initiative study." (PMID 30021611, 2018). "More work is needed to understand the root causes of the decreases in NPTX2 and GluA4 levels in Alzheimer’s disease." (PMID 28440224, 2017). "Now, in eLife, Paul Worley from the Johns Hopkins University School of Medicine and co-workers – including Mei-Fang Xiao and Desheng Xu as joint first authors – report that the loss of a protein called NPTX2 disrupts interneuron-mediated circuit activity in Alzheimer’s disease." (PMID 28440224, 2017). "Therefore, the possibility that NPAS-4 and NPTX-2 may serve as diagnostic and therapeutic biomarkers in Alzheimer’s disease warrants further investigation." (PMID 40563435, 2025). "Recent animal studies provide new evidence supporting the potential role of NPTX-2 in Alzheimer’s disease." (PMID 40563435, 2025). "Neuronal pentraxin 2 (NPTX2), a presynaptic protein involved in synaptic plasticity, has been linked to cognitive decline in Alzheimer's disease (AD) and other neurodegenerative disorders." (PMID 40522075, 2025). "In Alzheimer’s disease (AD), NPTX2 mRNA and protein levels are reduced in the postmortem neocortex compared to cognitively normal, age-matched controls." (PMID 41279079, 2025). "A decrease in NPTX2 was observed in the CSF of Alzheimer’s disease (AD) patients and NPTX2 showed robust correlations with cognitive function and hippocampal volume." (PMID 38367123, 2024). "A reduction of NPTX2 in CSF is also observed in Alzheimer disease (AD) and already in individuals with mild cognitive impairment compared to controls." (PMID 34838088, 2021). "Chitinase 3-like 1 (CHI3L1), chitinase 3-like 2 (CHI3L2), and neuronal pentraxin II (NPTX2) are inflammatory biomarkers of Alzheimer’s disease (AD)." (PMID 32066474, 2020). "Reduction of NPTX2 has also been correlated with neurodegenerative diseases, such as Alzheimer’s disease." (PMID 32396526, 2020). "Neuronal Pentraxin 2 (NPTX2) has recently been widely reported as a novel biomarker for Alzheimer's disease (AD), but its correlation with vascular dementia (VaD) has not been elucidated." (PMID 32748547, 2020). "A miR mechanism of NPTX2 down-regulation has also been previously detected in human brains following Alzheimer’s disease." (PMID 32396526, 2020). "This is consistent with another recent study showing that Alzheimer’s disease patients with higher initial levels of NPTX2 in their cerebrospinal fluid experience less memory decline over a two-year period." (PMID 28440224, 2017). "Our findings support the hypothesis that NPAS-4 and NPTX-2 are involved in the pathophysiological process of Alzheimer’s disease and may serve as potential biomarkers for early diagnosis and monitoring of disease progression." (PMID 40563435, 2025). "NPTX2 is a synaptic gene consistently reduced in Alzheimer’s disease (AD)." (PMID 41279079, 2025). "Also, CSF NPTX2 levels as measured by ELISA, have been found to be reduced in individuals with Alzheimer’s Dementia compared to age-matched controls." (PMID 40868076, 2025). "In addition, a recent study of the postmortem Alzheimer’s disease cortex shows profound reductions of NPTX2 and GluA435." (PMID 31267004, 2019). "A protein called NPTX2 may be a useful marker of neural circuit defects in patients with Alzheimer’s disease." (PMID 28440224, 2017).
Alzheimer disease (continued). "The ability to detect reduced NPTX2 in cerebrospinal fluid is relevant because targeting parvalbumin interneurons in particular, and circuit defects in general, is emerging as a potential way to treat cognitive impairments in patients with Alzheimer’s disease." (PMID 28440224, 2017). "NPTX2 binds to α-amino-3-hydroxy-5-methyl-4-isoxazolepropionic acid (AMPA) receptor subunit Glutamate receptor 4 (GRIA4) in neuronal tissues and has a presynaptic role in Pyramidal neurons with loss/loss of function associated with Alzheimer’s disease and Schizophrenia." (PMID 38875182, 2024). "Notably, whereas aberrant NPTX2 was similarly absent from neurons with tau inclusions in the hippocampus of patients with Alzheimer’s disease, we detected aberrant accumulation of NPTX2 in TDP-43 aggregate-bearing neurons in cases of Alzheimer’s disease with TDP-43 co-pathology." (PMID 38355792, 2024). "Interestingly, NPTX2 is downregulated in Alzheimer's disease." (PMID 31487305, 2019). "Together these results support the idea that amyloidosis does not immediately cause a decrease in NPTX2 expression, but rather that a drop in NPTX2 could be a “second hit” that collaborates with amyloidosis to lead to the defects in neural circuits and cognition seen in Alzheimer’s disease." (PMID 28440224, 2017). "Here, we report that Neuronal Pentraxin 2 (NPTX2; also termed Narp and NP2) is down-regulated in brain of human subjects with Alzheimer’s disease (AD)." (PMID 28440221, 2017). "The expression of NPTX2, a neuronal immediate early gene (IEG) essential for excitatory–inhibitory balance, is altered in the earliest stages of cognitive decline that anticipate Alzheimer’s disease (AD)." (PMID 41279079, 2025). "Another molecule called neuronal pentraxin 2 (NPTX2) is also a novel biomarker for Alzheimer disease, but no study has yet investigated its serum or aqueous humor levels in patients with glaucoma." (PMID 39917460, 2024). "NPTX2, which was decreased in ALS in our study, is involved in mediating excitatory neurotransmission and has been reported to be involved in various diseases such as Parkinson’s disease (PD), ischemia, Alzheimer’s disease (AD), and frontotemporal dementia." (PMID 37238921, 2023). "The expression of neuronal pentraxin 2 (NPTX2) is absent in Alzheimer’s disease, anxiety, and depression." (PMID 30833544, 2019). "C-Met, NPTX2, NEUROD6, and hyperpolarization-activated cyclic nucleotide-gated potassium channel 1 have all been found to be HCN1 in a study comparing gene expression in Alzheimer's and nondisordered Alzheimer's diseases." (PMID 35310907, 2022).
cognitive decline (26 papers, 2017 to 2026). "An increasing body of research has identified NPTX2 as a prognostic marker for cognitive decline associated with neurodegenerative, neuropsychiatric, and other neurological disorders." (PMID 40694319, 2025). "In line with the association at baseline, higher level of NPTX2 was associated with a slower rate of cognitive decline (St.B[SE] 0.22[0.11], p < 0.05)." (PMID 39121126, 2024). "NPTX2 levels also correlated with MRI measures of hippocampal volume, which is considered a marker of neurodegeneration and is linked to cognitive decline." (PMID 28440221, 2017). "Interestingly, reduced CSF levels of NPTX2 were associated with medial temporal lobe atrophy and cognitive decline in AD." (PMID 32066474, 2020). "This is supported by longitudinal NPTX2 decreases over time in two symptomatic mutation carriers and could reflect a link between progressive synapse pathology and cognitive decline; more longitudinal data is needed to confirm this." (PMID 32273328, 2020). "We hypothesize that lower serum NPTX2 levels are associated with impaired cognitive function in older adults with type 2 diabetes and may serve as a potential biomarker for diabetes-related cognitive decline." (PMID 40694319, 2025). "In line with reports of reduced CSF NPTX2 in AD and FTD associated with cognitive decline, the decrease of NPTXR in CJD suggests early synaptic degeneration driven by PrPSc‐induced toxicity." (PMID 41574640, 2026). "CSF NPTX2, previously shown to decrease in symptomatic FTLD and other neurodegenerative diseases, exhibited the strongest association with cognitive decline out of any individual protein." (PMID 38585969, 2024). "The downregulation of NPTX2 is a predictive marker for the progression from normal cognition to mild cognitive impairment, and cognitive decline is a typical symptom of PSP." (PMID 39342078, 2024). "Currently, NPTX2 has been confirmed as a closely related protein to the pathogenesis of AD and can predict cognitive decline in mild AD and MCI." (PMID 36793451, 2023). "NPTX2, is a promising biofluid surrogate marker of inhibitory circuit dysfunction and cognitive decline in different dementias." (PMID 34441934, 2021). "Together, these observations suggest that CHI3L1 and NPTX2 should be considered as novel biomarkers to improve the diagnosis and prediction of cognitive decline during the progression of AD." (PMID 32066474, 2020). "The reduction in brain NPTX2 expression is also reflected in the CSF and a recent study has shown that the ratio of CSF NPTX2 to CSF t-tau (neurodegeneration marker) was the best CSF predictor of cognitive decline in sporadic AD." (PMID 32807227, 2020). "Combining NPTX2 and Tau as a ratio had high diagnostic accuracy for AD or MCI, and NPTX2 predicted cognitive decline in both mild AD and MCI." (PMID 31853477, 2019). "Based on these observations, we propose that the cognitive decline observed in the diabetic group, alongside reduced NPTX2 levels, may be partially attributed to decreased insulin levels and/or impaired insulin function commonly seen in diabetes patients." (PMID 40694319, 2025). "The relationship observed between NPTX2 levels and cognitive impairment in diabetic patients provides preliminary evidence for a possible role of this biomarker in the pathophysiology of diabetes-related cognitive decline." (PMID 40694319, 2025). "This suggests that dysregulated synaptic adaptability mediated by NPTX2 downregulation could be a potential mechanism of the cognitive decline of PSP patients." (PMID 39342078, 2024). "Iowa State University's research also shows that high baseline levels of NPTX2 in AD may have neuroprotective effects and can predict lower degrees of medial temporal lobe atrophy and cognitive decline." (PMID 32748547, 2020). "•CSF synaptic biomarkers, particularly NPTX2, predicted cognitive decline." (PMID 31853477, 2019).
cognitive decline (continued). "The observed relationship between CSF levels of NPTX2 and cognitive decline may indicate progressive changes in synaptic circuitry dependent on the extent of overall neurodegeneration." (PMID 31853477, 2019). "Since NPTX2 reduction in AD occurs after accumulation of amyloid and parallels cognitive decline, we hypothesize that circuits can adapt to the effects of amyloid if pyramidal neurons are able to maintain circuit-specific expression of NPTX2." (PMID 28440221, 2017). "Previously, decline in NPTX2 levels has been found to be associated with cognitive decline, but we could not convincingly replicate these results." (PMID 39121126, 2024). "Moreover, degradation of NPTX2 showed a positive correlation with cognitive decline." (PMID 35997438, 2022). "The reduction of NPTX2 that is correlated with cognitive decline implicates a pathophysiological mechanism – failure of the adaptive function of pyramidal neurons to modify excitatory drive of fast spiking parvalbumin (PV) interneurons- that could potentially be targeted for therapeutics." (PMID 32552841, 2020). "Finally, we extend this framework to aging and AD, where medial temporal lobe hyperactivity and early PV dysfunction coincide with NPTX2 dysregulation, suggesting that restoring excitatory recruitment of PVs may help stabilize circuits and prevent cognitive decline." (PMID 42125538, 2026). "Synaptic biomarkers like neuronal pentraxins (NPs), including neuronal pentraxin 2 (NPTX2), and neuronal pentraxin receptor (NPTXR), offer insights into FTD pathology and cognitive decline." (PMID 38249293, 2023). "The significant correlation between CHI3L1 and NPTX2 in MCI and NCI suggests an interaction between astrocytes and neurons during the early stage of cognitive decline." (PMID 32066474, 2020). "Neuronal pentraxin-2 (NPTX2), a protein involved in inhibitory circuit dysfunction, is a promising biofluid surrogate marker of inhibitory circuit dysfunction and cognitive decline in sporadic AD, vascular dementia, genetic frontotemporal dementia, and Lewy body dementia." (PMID 34183050, 2021). "In DS, NPTX2 correlates with cortical atrophy and reduced glucose metabolism, but levels did not correlate with measures of cognitive decline." (PMID 34441934, 2021). "Although CSF chitinase and NPTX2 neuroinflammatory proteins are putative biomarkers related to the pathogenesis and cognitive decline seen in AD, there are virtually no detailed clinicopathological studies of these proteins in brain tissue during the clinical onset of AD." (PMID 32066474, 2020). "However, CSF NPTX2 levels did not correlate with measures of cognitive decline in our DS cohort." (PMID 34183050, 2021).
Cognitive impairment (25 papers, 2017 to 2025). Abnormal cognition is characterized by deficits in thinking, reasoning, or remembering. "Background and Objective: Neuronal pentraxin 2 (NPTX2) is associated with cognitive impairment in some neurodegenerative diseases." (PMID 39924979, 2025). "Among mutation carriers, NPTX2 correlated with cognitive impairment, grey matter volume of the whole brain as well as of frontal, parietal and temporal lobes and insula." (PMID 34460014, 2022). "If NPTX2 confers resilience, one would predict that risk factors for AD, such as older age, APOE-e4 genotype, and level of CR would be more strongly associated with cognitive impairment or risk of progression to MCI among individuals with low levels of NPTX2." (PMID 31231205, 2019). "Notably, lower baseline levels of CSF NPTX2 are associated with earlier progression from normal cognition to mild cognitive impairment (MCI), even after accounting for canonical amyloid and tau biomarkers." (PMID 41441216, 2025). "In particular, NPTX2 decreases paralleling disease progression and may reflect an association between synaptic disruption and cognitive impairment." (PMID 34460014, 2022). "NPTX2 may be implicated in the motor and cognitive impairment caused by dopaminergic nerve cell degeneration in the midbrain and synaptic alteration in the cerebral cortex, respectively." (PMID 34460014, 2022). "In addition to AD, NPTX2 is also associated with other forms of cognitive disorders." (PMID 32748547, 2020). "NPTX2 RNA and protein were significantly reduced in AD, and to a lesser extent in mild cognitive impairment (MCI) samples." (PMID 41279079, 2025). "Our study provides further evidence for the relationship between NPTX2 levels and cognitive impairment in AIS patients, while a further larger‐scale study is needed to verify our findings." (PMID 39924979, 2025). "This was further sustained by studies that found NPTX2 correlating with medial temporal atrophy, hippocampal volume and cognitive impairment." (PMID 34460014, 2022). "Previously, GluA4 and neuronal pentraxin 2 (NPTX2) showed limited potential as cerebrospinal fluid (CSF) markers of cognitive impairment in adults with DS." (PMID 34183050, 2021). "Therefore, decreased NPTX2 may be associated with a variety of cognitive disorders." (PMID 32748547, 2020). "In this cross-sectional study, rsfMRI scans were obtained from 130 older individuals (mean age = 69 years) with normal cognition (N = 113) and Mild Cognitive Impairment (N = 17); NPTX2 was measured in the same individuals in cerebrospinal fluid (CSF)." (PMID 31231205, 2019). "CSF levels of NPTX2 had a low to medium correlation with CSF levels of Tau and other synaptic biomarkers and decreased as cognitive impairment increased." (PMID 31853477, 2019). "Future studies with larger samples of participants and AD biomarkers are needed to confirm the role of NPTX2 in providing resilience to cognitive impairment in the face of pathology." (PMID 31231205, 2019). "Therefore, it is necessary to investigate and analyze the relationship between serum NPTX2 and poststroke cognitive impairment in patients with AIS." (PMID 39924979, 2025). "ROC curve indicated that serum NPTX2 predicted cognitive impairment in AIS patients." (PMID 39924979, 2025). "In recent years, NPTX2 has been suggested to provide additional and independent prediction of the onset of mild cognitive impairment (MCI) in cognitively normal individuals, and it might serve as an important prognostic biomarker during preclinical AD." (PMID 38367123, 2024). "The results of BIOCARD Research Team show that the expression level of NPTX2 in mild cognitive impairment (MCI) is significantly lower than that of normal people, and NPTX2 may participate in the regulation of cognitive tasks in MCI." (PMID 32748547, 2020). "Studies of DS brain suggest that NPTX2 down-regulation may contribute to cognitive deficits in young individuals and disease progression." (PMID 28440221, 2017).